MTOR (mechanistic target of rapamycin kinase)
Diseases named in the same sentence as MTOR in open-access papers (continued):
Sharing a sentence is not in itself a finding about the gene and the disease.
cancer (continued). "Interestingly, in both presented cases, Nucb2 impacts cancer progression via the mTOR pathway." (PMID 34073612, 2021). "However, these metabolic dependencies on mTOR signalling result in an imposed vulnerability in cancer cells that may provide a unique axis to tip the balance away from Foe and towards a Friend of cancer therapy." (PMID 34283054, 2021). "Upon receptor binding, EGF and TGF activate downstream mitogen-activated protein kinase (MAPK) and AKT-mammalian target of rapamycin (mTOR) pathways, which regulate apoptosis and cell proliferation, while inducible nitric oxide synthase (iNOS) modulates cellular bioenergetics pathways in cancer." (PMID 33842373, 2021). "Of significance and supporting a potential anti-cancer action of metformin is that LKB1 is a tumor suppressor and that mutations in LKB1 are observed in numerous cancers that result in the reduction of the inhibitory effect of the LKB1/AMPK pathway on the pro-proliferative signaling via mTOR." (PMID 34421827, 2021). "Moreover, the KEGG pathway enrichment analysis has suggested that target-based KEGG pathways were associated mainly in pathways in cancer, HIF-1 signaling pathway, Rap1 signaling pathway, ErbB signaling pathway, VEGF signaling pathway, mTOR signaling pathway, and PPAR signaling pathway." (PMID 35071383, 2021). "The PI3K/AKT and mTOR signaling pathways play a key role in cell proliferation, survival, and metabolism and are two of the most commonly dysregulated oncogenic pathways in cancers, including renal cell carcinoma, breast cancer, mantle cell lymphoma, adult soft tissue cancer, and bone sarcomas." (PMID 34716294, 2021). "The mechanism of the inhibitory effect of metformin on proliferation of cancer cells and tumor growth has been suggested to be associated with cell cycle arrest, promotion of apoptosis, inhibition of metastasis and induction of cellular stress through the AMPK/mTOR pathway." (PMID 34422646, 2021). "Hence, patient specific and clinically validated MTOR network models might serve in the future to support therapy decisions for the treatment of cancer and other diseases characterized by aberrant MTOR activity." (PMID 33544134, 2021). "Therefore, we can control cancer progression by modulating the AMPK/mTOR pathway." (PMID 33752745, 2021). "Phosphatidylinositol 3-Kinase (PI3K) and mTOR synergistically promote tumor progression and resistance to chemotherapy; therefore, inhibition of this pathway is an excellent treatment strategy and an efficient tool to avoid or circumvent cancer chemotherapy resistance." (PMID 33946916, 2021). "Indeed, this might explain why 4E-BP1 phosphorylation is unaffected by mTOR inhibitors in some cancer cells." (PMID 34011960, 2021). "Moreover, reduction in the phosphorylated/activated Akt and mTOR proteins’ expression may result in cancer cells being more sensitized to chemotherapies and reducing drug resistance." (PMID 33800129, 2021). "However, it is presently unclear whether and how lipolysis influences cancer metabolic signaling, including mTOR and AMPK signaling pathways." (PMID 33219129, 2021). "Hence, p38 and PI3K/Akt/mTOR can be key therapeutic targets for cancer treatment." (PMID 34371964, 2021). "Phosphatidylinositol-3-kinase (PI3K)/Akt and the mammalian target of rapamycin (mTOR) signaling pathway, which controls cell proliferation, is abnormally activated in several cancers and also in MM patients; therefore, a drug that inhibits this pathway might be effective in the treatment of MM." (PMID 34830893, 2021).
cancer (continued). "Therefore, we set out to determine whether the JNK signaling pathway was activated in cancer cells after treated with mTOR inhibitors and auranofin." (PMID 33754064, 2021). "Here, we further found that NO, in combination with PcrV, activates the PI3K/AKT/mTOR-glycolysis signaling pathway in TAMs, resulting in the formation of a PI3K/AKT/mTOR-glycolysis-NO feedback loop that increases NO generation and, consequently, NO-associated cytotoxicity against cancer cells." (PMID 34900687, 2021). "It is well established that mTOR is in the center of multiple signaling pathways where various extracellular and intracellular signals meet and become integrated for the organization of cellular metabolism and growth, and it is frequently dysregulated in metabolic disorders and cancer." (PMID 34572126, 2021). "The observed significant decrease in the presence of cpd29 + cholesterol + lovastatin compared to the cpd29 alone could possibly be due to the impact of lovastatin on other pathways, including inhibition of protein kinase B (AKT)/mammalian target of rapamycin (mTOR) in cancer cells." (PMID 34073320, 2021). "mTOR is involved in many cell functions, including growth, proliferation, apoptosis, and autophagy and its hyperactivation has been detected in several human cancers, thus representing, together with its upstream effectors, an important target for cancer therapy." (PMID 34885651, 2021). "Finally, the compounds were examined in vitro for inhibitory activities against mitochondrial NADH: ubiquinone oxidoreductase (complex I) by targeting the AMPK/mTOR signaling pathway and inhibiting hexokinase, a key glycolytic enzyme, to prevent the Warburg effect in cancer cells." (PMID 34500765, 2021). "Additionally, CD38 increases the phosphorylation of PI3K, AKT, and mTORC and upregulates the PI3K/AKT/mTOR pathway, which is related to metabolic reprogramming and proliferation of cancer cells, while such effects were significantly reversed with mTOR inhibitor, rapamycin." (PMID 33727923, 2021). "C3 may have exerted its anti-cancer actions by affecting the regulatory function of mTOR." (PMID 34208799, 2021). "We suggest that altered expression of cis-genes affected by underlying copy number aberrations may increase the activity of this pathwayDrugs that target the mTOR pathway have shown interesting results in other cancer types, which highlight its clinical importance." (PMID 34625038, 2021). "Activation of mTOR transduction may protect cancer cells from oxidative stress and ferroptosis." (PMID 33928101, 2021). "The phosphatidylinositol 3-kinase (PI3K)/AKT/mammalian target of rapamycin (mTOR) pathway is a well-known signaling pathway involved in cancer development and progression, including LUSC, indicating that this pathway may be a potential therapeutic target for LUSC patients." (PMID 34783291, 2021). "Moreover, we found that auranofin could block the increase of TrxR activity caused by mTOR inhibitors, and significantly increases the cytotoxicity of mTOR inhibitors in cancer cells." (PMID 33754064, 2021). "mTOR alters the metabolism of glucose, lipids, amino acids, and nucleotides according to the immediate demands of a cell, and the hyperactivation of its pathway may confer an advantage to cancer cells." (PMID 34309456, 2021). "However, in the high-TMEM176B-expression cancer cells AKT/mTOR pathway, activation could be compensated even under tamoxifen suppression." (PMID 34943938, 2021). "In this study we evaluated a number of cancer variants that are associated with resistance to endocrine therapy alone or in combination with or without PI3K/AKT/mTOR or CDK4/6 inhibitors, such as PTEN gene copy number loss and ESR1 activating mutations and copy number gain." (PMID 34471951, 2021).
cancer (continued). "Along with the critical role of the mTOR in cancer, recent studies have established an essential regulatory role of the mTOR in differentiation, activation, and functional properties of immune cells in which mTOR functions to coordinate and shape immune effector responses." (PMID 35250965, 2021). "Deregulation of the PI3K/AKT/mTOR signaling pathway by either the mutation or amplification of genes involved in the PI3K pathway, loss of the tumor suppressor PTEN, or overactivation of RTKs, has been observed in various cancer cells, contributing to tumor progression and metastasis." (PMID 34279440, 2021). "In addition, PI3K/AKT/mTOR signaling is deactivated in gambogic acid-treated cancer cells." (PMID 34575983, 2021). "Human cancer cells exposed to different concentrations of CT showed inhibition of major signaling pathways that are involved in multiple cellular processes such as, mammalian target of rapamycin (mTOR) in hepatic, gastric, pancreatic, soft sarcoma and prostate cancer." (PMID 33544704, 2021). "Furthermore, the Akt/mTOR cascade has emerged as a major regulator in cancer cell apoptosis." (PMID 33845796, 2021). "However, the phosphatidylinositol 3-kinase (PI3K)/AKT/mTOR signaling pathway plays a key role in cancer cell proliferation by regulating cell cycle modulation, and the inhibition may be toxic to normal cells." (PMID 33669811, 2021). "Furthermore, all compounds were investigated in silico for their ability to inhibit mitochondrial NADH: ubiquinone oxidoreductase (complex I) by targeting the AMPK/mTOR signaling pathway and inhibiting hexokinase, a key glycolytic enzyme to prevent the Warburg effect in cancer cells." (PMID 34500765, 2021). "Another strategy might be to concomitantly target mTOR with other cancer-specific dependencies." (PMID 34946644, 2021). "Thus, both Myc signaling and the PI3K/Akt/mTOR pathway are hyperactivated in cancer cells." (PMID 33946927, 2021). "Thus, the inhibition of the PI3K/AKT/mTOR signaling pathway might represent a possible therapeutic strategy for cancer treatment." (PMID 33923896, 2021). "Imbalances in the mTOR pathway including full inhibition or constitutive activation may disrupt the cellular homeostasis, leading to human diseases including but not limited to cancers, metabolic diseases, and aging and neurodegenerative disorders." (PMID 33670113, 2021). "Moreover, it has been shown that MYC proteins and the mTOR pathway cooperate with each other at the transcription and translation levels, respectively, to elevate overall protein synthesis rate, leading to increased cell proliferation and cancer progression." (PMID 34565342, 2021). "Together, these findings suggest that in HNSCC overactive PI3K/mTOR activity may establish of an immunosuppressive microenvironment in addition to its best known function in growth promotion, and that these two cancer-driver processes can be concomitantly suppressed by HER3 blockade." (PMID 33888713, 2021). "Moreover, MTOR pathway plays an important role in the treatment of human cancer." (PMID 33981239, 2021). "In turn, the mTOR pathway has been shown to be one of the most important pathways involved in the development and progression of cancer and in the maintenance and hallmarks of CSCs 50, implying that inhibition of the mTOR pathway could be a good therapeutic strategy to eradicate CSCs." (PMID 34405006, 2021). "This EPH receptor/SYK/DEPTOR mechanism, which bypasses the canonical pathway of mTOR activation, could potentially explain why so many cancers show constitutive mTOR activation without mutations in the PI3K/AKT pathway." (PMID 34634301, 2021). "Thus, glycolysis/OXPHOS inhibition by DDM and FDR treatment may induce cancer metabolic reprogramming via a novel PI3K/AKT/mTOR/P53NF-κB/VEGF pathway in BC cells." (PMID 34771733, 2021). "However, some cancers are not carrying mutations within this pathway but still harbor constitutive activation of mTOR." (PMID 34634301, 2021).
cancer (continued). "The PI3K/AKT/mTOR signaling pathway plays an important role in cell growth, proliferation, and survival, and it is one of the most commonly deregulated pathways found in human cancers, which makes components of this pathway attractive targets for anticancer therapy." (PMID 33572326, 2021). "Hence, combining mTOR inhibitors and cell-based immunotherapies in cancer treatment could be therapeutic strategies to increase the antitumor efficacy of immunotherapies." (PMID 35250965, 2021). "However, only several PI3K and mTOR inhibitors have been approved for cancer treatment." (PMID 34054126, 2021). "In this regard, a recent study demonstrated that the polyol pathway inhibitor enhances anti-cancer effects of sorafenib by blocking the mTOR pathway, suggesting that the activation of the polyol pathway in HCC may facilitate multityrosine kinase inhibitor escape via alternative pathways." (PMID 34885252, 2021). "As both CUR and CA individually were found to affect mTOR and its downstream effectors in various cancer cell types, we hypothesized that the polyphenol-induced changes in the mitochondrial activities observed in our study may, at least in part, be related to the changes in mTOR signaling." (PMID 34679726, 2021). "In addition, CNV of mTOR pathway genes are present in most cancers." (PMID 34194607, 2021). "Since mTOR has essential roles in cell proliferation, cell transformation, protein synthesis, and the nutritional level sensory response, mTOR allosteric inhibitors that suppress mTORC1 activity have been considered to be able to potentiate in cancer growth suppression." (PMID 33669811, 2021). "Moreover, there is also evidence that inactivation of mTOR may lead to differentiation of cancer stem cells derived from the nervous system." (PMID 33804163, 2021). "Phosphatidylinositol-3-kinase (PI3K)/AKT/mammalian target of rapamycin (PI3K/AKT/mTOR) signaling is critical to many aspects of tumor cell growth and survival and therefore could be likely involved in the survival of irradiated cancer cells." (PMID 33898418, 2021). "Therefore, mTOR activity may directly or indirectly reflect the nutritional and functional status of immune cells and cancer cells." (PMID 35250965, 2021). "In addition, the regulation of the snoRNA class is dominated by the cancer-supporting mTOR signalling pathway, and they may have particular significance to immune cell function and anti-tumour immune responses." (PMID 34440039, 2021). "Therefore, inhibitors of mTOR signaling have gained plenty of attention in cancer treatment." (PMID 34066403, 2021). "The IGF-1/PI3K/AKT/mTOR signaling pathway may be one of the important mechanisms of cancer." (PMID 34696683, 2021). "Thus, investigating more potent mTOR inhibitors for cancer treatment remains an ongoing challenge." (PMID 35155187, 2021). "Interestingly, resistance to mTOR inhibitors in TNBC was accompanied by the appearance of Notch-dependent cancer stem-like cells (CSCs), suggesting that Notch inhibitors may be combined with mTOR/AKT inhibitors." (PMID 34359640, 2021). "Interestingly, IL-6 was also found to induce the production of Survivin, an inhibitor of apoptosis, in cancer cells; the authors also identified that mTOR/4E-BP1 signaling is activated in cancer cells as a response to CAF-secreted factors and plays a role in imparting chemoresistance." (PMID 34646829, 2021). "Therefore, targeting mTOR signaling represents an attractive therapy in cancer." (PMID 33801030, 2021). "In addition, the mTOR pathway also enhances aerobic glycolysis by upregulating PKM2 via c-Myc induction, suggesting that inhibition of the mTOR pathway by pharmacological components (such as RapaLinks) might have therapeutic importance in cancer treatment." (PMID 33925206, 2021).
cancer (continued). "It is noteworthy that, like cancer cells, activated T cells also exhibit the Warburg Effect or aerobic glycolysis which is characterised by elevated glycolysis and downregulated oxidative phosphorylation and is driven by mechanistic target of rapamycin (mTOR) signalling." (PMID 34268109, 2021). "Furthermore, studies using cell line models have shown that fibrinogen may promote carcinoma cell motility by inducing the EMT via the p-AKT/p-mTOR pathway." (PMID 34056114, 2021). "Therefore, the PI3K/AKT/mTOR signaling pathway became a popular target for new drugs in cancer." (PMID 32962206, 2020). "Cumulative evidence has shown that the activation of the PI3K/mTOR signaling pathway plays an important role in the occurrence of malignant tumors; hence targeting suppression of this signaling pathway might be a promising therapeutic strategy for cancer treatment." (PMID 33080824, 2020). "Additionally, recent mouse studies of mTOR signaling, a key regulator of protein synthesis that is suppressed by inflammatory mediators in cancer cachexia, have shown that muscle-specific deletion of mTOR or Raptor results in muscle fibrillation and NMJ fragmentation." (PMID 31794435, 2020). "We hypothesized that the strong disruptive effects of these molecules on the endolysosomal compartment and mTOR signaling might also create additional vulnerabilities in cancer cells independent of their MAPK pathway mutational status." (PMID 32531927, 2020). "Moreover, CA9 expression potentially contributes to the regulation of cancer cell differentiation and mediates tumour‐associated genes and signalling pathways, including apoptosis, hypoxia, G2M checkpoint, PI3K/AKR/mTOR signalling and TGF‐beta signalling pathways." (PMID 32299152, 2020). "Based on our data we could hypothesize that the types of complex I dysfunctions that stimulate cancer progression would correlate with overstimulation of mTOR activity that initiates downstream signalling events promoting apoptosis but also apoptosis-induced proliferation." (PMID 32157127, 2020). "Since the immune-checkpoint PD-1L increases the glycolysis in cancer cells by activating Akt/mTOR pathway, the use of immune-checkpoint inhibitors may relieve the competition for glucose between cancer cells and T-lymphocytes, restoring the anti-tumor efficiency of the latter." (PMID 33291643, 2020). "Given that C. jejuni induced pathologies include the activation of the mammalian target of rapamycin (mTOR) and were ameliorated by rapamycin treatment in IL-10−/− mice, it is noteworthy that urolithin-A was reported to downregulate mTOR dependent pathways in cancer cells." (PMID 33374868, 2020). "Therefore, AKT/mTOR pathway represents the major targets for anti-cancer drugs development." (PMID 33116125, 2020). "Thus, interrupting mTOR with novel therapeutic could induce a reduction of stemness of cancer cells and sensitize them to the therapies." (PMID 33665161, 2020). "Therefore, mTOR signaling has been described as an important target for cancer diagnosis." (PMID 31894839, 2020). "In conclusion, we revealed the essential role of exosomes in communication between cancer cells and demonstrated that MALAT1 expression in exosomes was required for inducing aggressiveness phenotype by regulating FUT4-associated fucosylation and PI3K/Akt/mTOR pathway." (PMID 32209115, 2020). "PI3K/Akt/mTOR signaling pathway is commonly activated and suppression of its activation may inhibit cells proliferation and metastasis in cancers of the lung, colorectal, esophagus, breast, liver, and kidney, which has been considered a promising therapeutic target." (PMID 32655659, 2020). "This dichotomy may be driven by two forces: 1) the intrinsic properties of cancer cells, such as the mTOR activities and EMT (changing the EMT status of the tumor cells could alter the type of myeloid being recruited as shown in our work), and 2) the mutually negative impact between TAMs and TANs." (PMID 33343560, 2020).